MIR4420 (microRNA 4420)
Synonyms: hsa-mir-4420; mir-4420
Gene: MicroRNA gene on chromosome 1 (30,739,156 to 30,739,232, reverse strand). Ensembl gene ENSG00000264773.
Homologues: Orthologues: chimpanzee MIR4420 (100% identical).